PIK3CA (phosphatidylinositol-4,5-bisphosphate 3-kinase catalytic subunit alpha)
Diseases named in the same sentence as PIK3CA in open-access papers (continued):
Sharing a sentence is not in itself a finding about the gene and the disease.
breast cancer (continued). "PIK3CA, the gene coding for the p110α subunit of phosphoinositide 3-kinase, is frequently mutated in a variety of human tumors including breast cancers." (PMID 22666336, 2012). "For example, the frequency of PIK3CA mutations in a previous study of 366 ER+ breast cancer patients was 38.5%." (PMID 22970388, 2012). "In particular, Kalinsky and colleagues studied a series of 590 patients with breast cancer with a median follow-up of 12.8 years and found 32.5% of PIK3CA mutations." (PMID 22330809, 2012). "PIK3CA mutations have been observed in up to 40% of breast cancers including both ductal and lobular histological subtypes." (PMID 22666336, 2012). "Because we have previously shown that hyperactivation of the EGFR pathway mimics oncogenic PIK3CA mutations, our results would suggest that breast cancers with mutant PIK3CA and AR expression would have a favorable therapeutic response to AR ligand binding." (PMID 22321971, 2012). "In parallel, HER2-amplified breast cancer cell lines containing PIK3CA hotspot mutations more significantly resisted TZMB than mutant-free cells." (PMID 22482061, 2012). "The independent prognostic value of PIK3CA mutation status in ERBB2-positive breast cancer patients should be now confirmed in larger series of patients included in randomized prospective ERBB2-based clinical trials." (PMID 22330809, 2012). "We therefore determined the glucose growth dependency of six colon and breast cancer cell lines, all containing endogenous PIK3CA mutations." (PMID 23028762, 2012). "PIK3CA activating mutations have been reported to associate with shorter time to progression (TTP) in Trastuzumab-treated breast cancer." (PMID 22935382, 2012). "Recently, gain-of-function mutations in PIK3CA have been found in several cancers, including breast cancer." (PMID 22330809, 2012). "PIK3CA mutations are observed in 32% of colorectal cancers, 31% of endometrial cancers and 14% of breast cancers." (PMID 22994622, 2012). "PIK3CA is the oncogene showing the highest frequency of gain-of-function mutations in breast cancer, but the prognostic value of PIK3CA mutation status is controversial." (PMID 22330809, 2012). "Subgroup analysis of patient survival identified PIK3CA mutation status as an independent prognostic value in patients with ERBB2+ breast cancer." (PMID 22330809, 2012). "PIK3CA mutations occur in about 25−30% of breast cancers, with numbers varying depending on the specific patient population and also the types of mutations that are included in the analysis." (PMID 22970388, 2012). "PIK3CA that encodes the catalytic subunit of PI3K is a gene frequently mutated in breast cancer and promotes TZMB insensitivity in BC cells in vitro." (PMID 22482061, 2012). "While mutations in the PI3 kinase gene (PIK3CA) are common in breast carcinoma, somatic mutations in AKTs are rare." (PMID 23056620, 2012). "In breast carcinomas, the majority of mutations have been identified in the helical domain (exon 9, 37%) and in the kinase domain (exon 20, 63%) of PIK3CA." (PMID 23056620, 2012). "Although the first two stages of our analysis suggest an association between PIK3CA and breast cancer risk, our inability to confirm this finding in the BCAC studies suggests that the result should be interpreted with caution." (PMID 22033276, 2011). "A subset of glandular cells expressed the estrogen receptor, which matches molecular subtype data in humans, where PIK3CA mutations are commonly found in ERα-positive luminal breast cancers." (PMID 21646685, 2011). "PIK3CA mutations are the most common genetic alterations of this pathway in breast cancer, where ≥80% occur within “hot spots” of exons 9 and 20, corresponding to the helical (E542K and E545K) and kinase (H1047R) domains of p110α." (PMID 22248929, 2011).
breast cancer (continued). "PIK3CA hotspot mutation analysis was performed in 51 recurrent or metastatic breast cancers and correlated with ER status and survival." (PMID 21362200, 2011). "Here we report an association between inherited variation in the oncogene PIK3CA and risk of breast cancer in a large, three-stage analysis utilising nearly 75 000 subjects from 27 case–control study studies." (PMID 22033276, 2011). "PIK3CA mutations occur in many breast cancer subtypes but are rarely, if ever, seen in claudin-low tumors." (PMID 21646685, 2011). "Of four PIK3CA haplotype-tagging SNPs, rs1607237 was significantly associated with risk of breast cancer in MCBCS (OR=0.85, 95% CI 0.73–0.98, P=0.023)." (PMID 22033276, 2011). "Functional evaluation of this variant is needed to fully understand the relationship between inherited PIK3CA variation and breast cancer risk." (PMID 22033276, 2011). "We have examined this question in ER+/HER2-negative MCF7 human breast cancer cells which also harbor an activating E545K mutation in PIK3CA (p110α)." (PMID 22248929, 2011). "The presence of activating mutations conferring a better prognosis has been reported with EGFR mutations in non-small cell lung cancer (NSCLC) and with PIK3CA mutations in breast cancer." (PMID 21352589, 2011). "PIK3CA mutations are found in tumors from most subtypes, which explains why this gene scored as one of the two most commonly mutated genes in breast cancer." (PMID 21646685, 2011). "Recent studies using HER2-amplified breast cancer cell lines showed that those cell lines with PIK3CA hotspot mutations were significantly more resistant to trastuzumab than those without mutations." (PMID 22295219, 2011). "Gain-of-function mutations in PIK3CA have recently been found in several malignancies, including breast cancer." (PMID 21209903, 2010). "Somatic gain-of-function mutations of PIK3CA are associated with an increased activation of PI3K in breast cancers." (PMID 20836878, 2010). "MCF-7 and BT-474 breast cancer cell lines have mutated forms of PIK3CA, which can render these cells resistant to Ly294002-mediated cell cycle arrest." (PMID 18652687, 2008). "It has been previously demonstrated in breast cancer and glioblastoma that PIK3CA mutations and PTEN loss are virtually mutually exclusive, suggesting that abrogation of just one of these proteins is sufficient for tumorigenesis." (PMID 18208621, 2008). "Much larger studies will be needed to address the predictive value of PIK3CA mutations in different molecular subsets of breast cancer in the context of different chemotherapies." (PMID 18371219, 2008). "We examined PIK3CA mutation status in 140 patients with stage II–III breast cancer and correlated the results with clinical and pathological variables, including response to preoperative chemotherapy." (PMID 18371219, 2008). "The PI3K signalling pathway is frequently deregulated in human solid tumours including breast cancers through Akt1 or PIK3CA (catalytic subunit of PI3K) mutations, HER2 overexpression and PTEN loss or mutation." (PMID 19055754, 2008). "In breast cancer, PIK3CA mutations occur in approximately 18% to 40% of human cases and are also observed in up to 50% of breast cancer cell lines." (PMID 18371219, 2008). "Mutations in PIK3CA were also identified in glioblastoma, gastric cancer, breast cancer and lung cancer." (PMID 19384426, 2007). "Another study reported PIK3CA somatic mutations in hepatocellular carcinomas (35.6%), breast carcinomas (26.9%), gastric carcinomas (6.5%), acute leukemias (1.1%) and non-small-cell lung cancers (1.3%)." (PMID 19384426, 2007).
breast cancer (continued). "In an effort to identify the genetic alterations of the PIK3CA gene in breast cancer, we determined the mutation frequency and the change in the gene copy number of PIK3CA in a set of primary breast tumors and breast cancer cell lines." (PMID 16168105, 2005). "The 8% mutation rate of PIK3CA in breast cancer, reported in a previous study, was underestimated, probably because of the smaller number of cases examined." (PMID 16168105, 2005). "To determine the relation between somatic mutation and gain of gene copy number of PIK3CA gene in breast cancer, we integrated our mutation and gene copy number data." (PMID 16168105, 2005). "Only 12 cases of breast cancer were examined, of which one was found to harbor a mutation in PIK3CA." (PMID 16168105, 2005). "The frequent and clustered mutations within PIK3CA make it an attractive molecular marker for early detection of breast cancer." (PMID 16168105, 2005). "First, we show a 20.6% mutation rate of the PIK3CA gene in breast cancer, indicating that PIK3CA mutation is a frequent genetic alteration in breast cancer." (PMID 16168105, 2005). "The frequent and clustered mutations within PIK3CA make it an attractive molecular marker for early detection and a promising therapeutic target in breast cancer." (PMID 16168105, 2005). "This study aims to evaluate the cost-effectiveness of inavolisib plus palbociclib-fulvestrant versus palbociclib-fulvestrant for treating advanced HR+/HER2-breast cancer patients with PIK3CA mutations from both United States (U.S.)and Chinese healthcare system perspectives." (PMID 41496420, 2026). "Currently, there is a lack of Phase III study data comparing the triple regimen directly with alternative first-line treatment strategies for HR+/HER2- advanced breast cancer patients with PIK3CA mutations and endocrine resistance, precluding direct head-to-head cost-effectiveness comparisons." (PMID 41496420, 2026). "Studies have demonstrated PIK3CA mutations to be crucial factors in breast cancer progression." (PMID 41476220, 2026). "Therefore, under WTP thresholds of $150,000/QALY in the U.S. and $40,334/QALY in China, the inavolisib triple regimen was not economically viable as first-line therapy for advanced HR+/HER2- breast cancer patients with PIK3CA mutations in both countries." (PMID 41496420, 2026). "Previous studies have reported that HER2‐positive breast cancers harboring PIK3CA mutations may exhibit reduced sensitivity to trastuzumab, pertuzumab, and lapatinib." (PMID 41556040, 2026). "Also, mouse models carrying a combination of Pten mutations with other oncogenic drivers such as mutant Pik3ca and Erbb2 have accelerated development of mammary tumours." (PMID 41215730, 2026). "This indirect, upstream targeting approach differentiates losartan from direct PI3K/Akt inhibitors like alpelisib, which is FDA‐approved for PIK3CA‐mutated breast cancer, and may lead to distinct efficacy and resistance profiles." (PMID 41486497, 2026). "Consequently, Alpelisib in combination with Fulvestrant gained FDA and EMA approval for this group of PIK3CA-mutated breast cancer patients." (PMID 40260297, 2025). "We also investigated whether PIPP or PTEN expression or PIK3CA mutation correlated with AKT activation in human breast cancer cell lines following serum stimulation." (PMID 41408399, 2025). "Although the detection of gene mutation status has been used as an important therapeutic strategy in the clinical treatment of a variety of tumors, the relationship between PIK3CA mutations and clinicopathological characteristics and prognosis of breast cancer patients is still controversial." (PMID 40472482, 2025). "Thus, a history of a breast cancer diagnosis before UC diagnosis cannot explain the lower frequency of PIK3CA mutations observed in TA-UC compared to de novo UC." (PMID 40846762, 2025).
breast cancer (continued). "First, while mutations such as PIK3CA H1047R are frequently observed in breast cancer and may indicate less aggressive disease biology, their integration into workflows to select patients for local therapy requires further prospective validation." (PMID 40723288, 2025). "PIK3CA mutation spectrum stratified by molecular subtypes of breast cancer (n= 196)." (PMID 41415546, 2025). "Myeloid-derived suppressor cells (MDSCs) are one of the main immunosuppressive cell subsets within the tumor microenvironment (TME) and we previously demonstrated that PIK3CA mutation could induce immune evasion by recruiting MDSCs in breast cancer." (PMID 41281644, 2025). "Oncogene PIK3CA is found to be highly mutated in almost one-third of breast cancer cases." (PMID 40282403, 2025). "Studies have shown that in hormone receptor–positive (HR+) breast cancer, PIK3CA mutations activate the PI3K pathway, promoting ligand-independent estrogen receptor (ER) activation, thereby leading to endocrine therapy resistance and accelerating disease progression." (PMID 40535135, 2025). "Consequently, investigating the mechanisms by which MDSCs directly regulate breast cancer cells to promote tumor progression is crucial for developing an effective therapeutic strategy for PIK3CA-mutated HR + breast cancer patients." (PMID 41281644, 2025). "Additionally, with PIK3CA-mutant HER2+ being a common mutation profile in breast cancers, HER2+ inhibitors in combination with alpelisib are being investigated in multiple clinical trials [NCT04208178, NCT05230810, NCT02167854, NCT05063786]." (PMID 40564038, 2025). "The PAM pathway is the most commonly activated signaling pathway in breast cancer, which may result from activating mutations in the PIK3CA and AKT1 genes or inactivating alterations in the PTEN gene." (PMID 40206206, 2025). "The DMBA-induced breast cancer model is a widely used system that closely mimics human breast tumors, particularly estrogen receptor-positive (ER+) types, due to its high reproducibility and molecular similarity, including frequent Pik3ca and Pten mutations." (PMID 40430573, 2025). "Approximately 30% of patients with HER2+ breast cancer harbor activating PIK3CA mutations." (PMID 40303296, 2025). "Here we show that the FOXO3-FOXM1 transcription factors are pivotal drivers of response to drugs that target p110α or AKT in ER+ breast cancer models with PIK3CA activating mutations or in drugs that target AKT in models with PIK3CA activating mutation and compromised PTEN expression." (PMID 40263319, 2025). "In addition, the effects of PIK3CA mutation on the prognosis of different subtypes and different periods of breast cancer are also different." (PMID 40472482, 2025). "This paradoxical observation has also been reported in breast cancer studies of PIK3CA, where some studies found that in early‐stage breast cancer, PIK3CA kinase domain mutations reduced cell chemotaxis, thereby decreasing cancer cell migration and metastasis and improving prognosis." (PMID 40817602, 2025). "HR+/HER2- breast cancer patients had the highest probability of PIK3CA mutation (46.7%), and HER2+ breast cancer patients had the lowest probability of PIK3CA mutation (29.0%), but the difference was not statistically significant compared with other subtypes of breast cancer patients (p > 0.05)." (PMID 40472482, 2025). "Additionally, PIK3CA mutations have been linked to a reduced risk of local recurrence in breast cancer, and a potential role of the PI3K pathway in modulating radiosensitivity has been reported." (PMID 41465267, 2025).
breast cancer (continued). "ddPCR has been applied to quantify oncogene mutations in ctDNA, such as PIK3CA mutations in early-stage breast cancer, achieving a sensitivity of 0.01 % for detecting each of the three PIK3CA hotspot mutations and a specificity exceeding 99 % compared to tumor tissue." (PMID 40144458, 2025). "Elevated PI3K–AKT activity may be mediated by loss-of-function mutations in PTEN (in up to 5% of HER2+ breast cancers) or activating mutations in the PIK3CA gene (seen in approximately 20% of HER2+ cases)." (PMID 40940886, 2025). "In addition, findings assessing the molecular landscape of HER2-positive breast cancer patients reported an elevated frequency of PIK3CA mutations (61.5%), but the difference to PIK3CA wild-type was not significant." (PMID 40227634, 2025). "PIK3CA mutations are common in breast cancer; however, their direct relationship with TMB remains unclear." (PMID 39466567, 2025). "Likewise, in HER2-positive breast cancer, the presence of PIK3CA mutations or PTEN loss can reduce sensitivity to HER2-targeted agents." (PMID 40076838, 2025). "There is some evidence that the occurrence of PIK3CA mutations in breast cancer may have interethnic differences." (PMID 40507317, 2025). "Advances in imaging and molecular profiling suggest that oligometastatic breast cancer might represent a distinct biological subtype, with potential biomarkers including PIK3CA mutations and YAP/TAZ expression." (PMID 40723288, 2025). "Notably, PIK3CA mutations are present in approximately 30%–40% of breast cancers, and these mutations are associated with poor prognosis and resistance to standard therapy." (PMID 40434054, 2025). "Mutations in PIK3CA usually result in poor prognosis in breast cancer." (PMID 40142329, 2025). "In addition, CALM1 has been implicated in AKT regulation, especially in PIK3CA-mutated breast cancer." (PMID 40823088, 2025). "PIK3CA is the second most commonly mutated gene in breast cancer." (PMID 40002579, 2025). "Breast cancer exhibits PIK3CA mutations at a frequency of approximately 34%." (PMID 40142329, 2025). "Although combined alpelisib and fulvestrant therapy has been approved by the FDA for the treatment of PIK3CA-mutated HR+ HER2− breast cancer, side effects, including on-target side effects such as hyperglycemia, restricted the maximum dose and thus clinical efficacy of alpelisib." (PMID 39717717, 2025). "PIK3CA somatic mutations occur in about 30–50% of the relapsed HR+/HER2− breast cancer population." (PMID 40244377, 2025). "Regarding breast cancer ctDNA can be usefully adopted to evaluate PIK3CA gene mutational status." (PMID 40219616, 2025). "Second, we systematically reviewed clinical trials targeting PIK3CA mutations in breast cancer." (PMID 40142329, 2025). "PIK3CA mutation analysis was performed in 34 pairs (primary breast carcinoma and corresponding LR)." (PMID 39929942, 2025). "Recently, a phenomenon of multiple (usually two) co-occurring PIK3CA mutations was described in breast cancer and other tumor types: these mutations occur mainly in cis, are mutually exclusive with other driver genetic alterations, and confer increased sensitivity to PI3K inhibition." (PMID 40507317, 2025). "Research regarding PD-L1 expression, immune cells and PIK3CA mutations might have an impact on how to determine therapeutic approaches for patients with HR+/HER2- breast carcinoma." (PMID 41096755, 2025).